BRCA1 (BRCA1 DNA repair associated)
Diseases named in the same sentence as BRCA1 in open-access papers (continued):
Sharing a sentence is not in itself a finding about the gene and the disease.
cancer (continued). "While promoter methylation of BRCA1 is frequently observed across cancers, BARD1 promoter methylation is comparatively rare, suggesting that preservation of BARD1 expression may contribute to its tumor suppressor function." (PMID 41009605, 2025). "Such a survival advantage might reflect the specific ability of RIF1-L to interact with BRCA1, which promotes recombination-mediated recovery of broken replication forks, which arise under the prolonged stress conditions characteristic of cancer cells." (PMID 40806439, 2025). "While cells with functional BRCA1/2 can efficiently HR to maintain genomic stability, BRCA1/2-deficient cancer cells are not." (PMID 41304924, 2025). "Nonetheless, it remains possible that other germline variants in the BRCA1 5’ UTR region are associated with promoter hypermethylation and may be connected with cancer risk in different populations." (PMID 40495194, 2025). "PARP inhibitors are particularly effective for patients with mutant BRCA1/2 cancers." (PMID 41049848, 2025). "BRCA1 and BRCA2 proteins are required for homology-directed repair (HDR) of DNA double-strand breaks (DSBs), and germline mutations in BRCA1 or BRCA2 genes predispose individuals to breast, ovarian, and other cancers." (PMID 40669753, 2025). "Thus, BRCA1 cell models that are ER- and PR-negative are needed to gain more in-depth knowledge about the steps leading to cancer in ER-negative cells." (PMID 41283387, 2025). "Using these samples, we mapped and characterized the pattern of DNA DSBs or “breakome”, and analyzed how specific BRCA1 or BRCA2 mutations may impact early mammary carcinogenesis, and ultimately could play a role in early cancer detection." (PMID 41350536, 2025). "This complexity is consistent with BRCA1’s substantial biological functions in cancer." (PMID 41354912, 2025). "We have proposed an alternative approach, which is based on the comparison of early-onset versus late-onset cancer patients, thus assuming that the age at diagnosis may serve as a surrogate of BRCA1/2 penetrance." (PMID 41374957, 2025). "Besides that, resveratrol is a potent inhibitor for the initiation and progression of BRCA1 mutant cancer both in vitro and in vivo, making it an excellent molecule for targeted therapy." (PMID 40136510, 2025). "This discrepancy in regional distribution between BRCA1 and BRCA2 variants could be attributed to factors such as the diversity of the genome, gender differences, and cancer types." (PMID 40249378, 2025). "The authors speculated that improvements in survival may stem from earlier cancer detection, BRCA1 cancer sensitivity to chemotherapy, effective treatments, and potential bias from proactive high-risk participants in screening and treatment." (PMID 41083355, 2025). "Tumors with BRCAness—tumors that share molecular features of germline BRCA1/2-mutant cancers—may share therapeutic vulnerabilities with BRCA1/2 mutant cancers to PARPi treatment." (PMID 41359628, 2025). "Poly(ADP-ribose) polymerase (PARP) inhibitors (PARPi) induce cell death by exploiting the absence of homologous recombination in cancer cells harboring mutations in the BRCA1/BRCA2 genes." (PMID 41347092, 2025). "However, additional genes such as BARD1, whose protein product interacts with BRCA1 via its N-terminal RING domain, have been implicated as low-penetrance contributors to cancer risk." (PMID 41301857, 2025). "Since cancer cells are known for exhibiting cell-type-dependent behavior, it may be questioned whether reported results on BRCA1-induced metabolic reprogramming may be generalized to other cancer cell types." (PMID 40863152, 2025).
cancer (continued). "Our findings are consistent with prior studies showing higher RS results in patients with PVs in BRCA1/2; however, this is the first study to compare the single-gene expression of the cancer genes within the assay between patients with PVs in BRCA1/2 and the general 21-gene-tested populations." (PMID 38568368, 2024). "In our previous article, using data from the Hospital-based Epidemiological Research Program at Aichi Cancer Center (HERPACC), we assessed the impact of Germline Pathogenic Variants (GPVs) of cancer-predisposing genes, such as BRCA1 or BRCA2, on breast cancer risk." (PMID 38403691, 2024). "For example, patients with hereditary BRCA1/BRCA2 mutations can be diagnosed with cancer approximately 2 years earlier than patients without such mutations." (PMID 38279352, 2024). "DH PSV in either the BRCA1 or BRCA2 genes with other cancer susceptibility genes or two non-BRCA cancer susceptibility genes have been reported less frequently, especially in populations not exhibiting founder PSVs." (PMID 39102164, 2024). "One potential explanation for the observed association between high BRCA1 expression and a poor prognosis in patients with BRCA is that elevated levels of BRCA1 could play a protective role in preventing additional DNA damage in cancer cells." (PMID 38224491, 2024). "Additionally, oxidative stress plays a significant role in the pathogenesis of BRCA1-related cancers." (PMID 39300540, 2024). "Moreover, studying the molecular effects of BRCA1 epimutation in WBCs has shown that there are cancer-related molecular changes that can occur in adult carriers and, more importantly, in newborn carriers." (PMID 38542081, 2024). "BRCA1 (breast cancer gene 1), BARD1 (BRCA1 associated RING domain 1) and MDM2 (mouse double minute 2 homolog) are well-known proteins containing this domain which play important roles in cancer progression." (PMID 39119040, 2024). "A limited number of studies have investigated the role of BRCA1 in cancer metabolism." (PMID 38745772, 2024). "It produces syndromes associated with a moderate risk of cancer due to a limited hyper-recombination accompanied by a lack of cell cycle control (e.g., category 2 syndromes like BRCA1 and BRCA2 mutations)." (PMID 39335159, 2024). "This might be due to the different cellular localization of BRCA1 ∆11 isoforms compared to the WT protein, but the mechanism by which BRCA1 localization influences cancer development and therapy response remains unknown." (PMID 39062754, 2024). "Synthetic lethal approaches being investigated in tumor-agnostic studies include PARP inhibitors for BRCA1/2- or ATM-mutant cancers; ATR inhibitors for ATM-mutant cancers; and PKMYT1 inhibition for solid tumors with CCNE1 amplification, FBXW7 loss, and PPP2R1A mutations (NCT04855656)." (PMID 38938274, 2024). "However, in terms of age, the group carrying BRCA1 and BRCA2 co-mutations had a significantly earlier age of cancer onset than the rest patients (mean age, 51 VS 54.5 years, Wilcoxon test P value 7.30e-03)." (PMID 38817903, 2024). "The status of hCCAR2 may dictate cancer progression and drug resistance in the BRCA1/2-null background." (PMID 38172598, 2024). "In vitro fertilization (IVF) is also an important endocrine intervention that might affect cancer risk; however, since data on IVF, particularly regarding cancer risk for BRCA1/2 mutation carriers, are sparse, we decided to focus on HRT and HC." (PMID 38892081, 2024). "More unexpected, individual with biallelic mutations of BRCA1 without cancer nor clinical FA-like features were also reported." (PMID 39596525, 2024). "In individuals without a cancer diagnosis but with a known BRCA1/2 pathogenic variant in their family, the overall mutation rate is 23.9%." (PMID 38753118, 2024).
cancer (continued). "Further understanding of these mechanisms may eventually pave the way for improved personalized cancer therapy of PALB2 mutation carriers, and possibly also to carriers of functionally related cancer susceptibility gene defects in e.g., BRCA1 and BRCA2." (PMID 38597967, 2024). "Interestingly, in chromosomally unstable cancers like those containing BRCA1/2 PVs, ectonucleotide pyrophosphatase/phosphodiesterase 1 (ENPP1) has been shown to be upregulated." (PMID 39682099, 2024). "Germline mutations in BRCA1 and CHEK2 may lead to homologous recombination repair deficiency and cell cycle disorder, eliciting cancer at an early age." (PMID 38509102, 2024). "Considering PACC is likely to be positive for BRCA1/2 mutations responsible for HBOC, resectable cases should be closely followed up with the prospect that the PACC may be synchronous or metachronous cancer." (PMID 39188100, 2024). "Furthermore, a strong positive correlation was found between CA15-3 levels and BRCA1 expression in advanced cancer stages." (PMID 39742378, 2024). "This is the first reported case where two BRCA1 variants with demonstrated functional impact are identified in trans in a male patient with an apparently normal clinical phenotype and no BRCA1-associated cancer." (PMID 38195559, 2024). "Our analysis also suggests that the subsequent relapses in 2 patients with germline BRCA1 mutation were derived from the primary index tumor and were not second cancers." (PMID 38315150, 2024). "Likewise, various alterations of BRCA1 are associated with CMT, especially with the loss of proper expression and function in malignant tumors." (PMID 39696035, 2024). "We aimed to assess the cell autonomous and cell-nonautonomous implications of a germline BRCA1 mutation in the context of cancer immunosurveillance of CD3− CD56+ natural killer (NK) cells." (PMID 38539519, 2024). "In cases of promotor hypermethylation, like BRCA1 and RAD51C in some cancers, loss of methylation might also reverse the HRD phenotype." (PMID 39119040, 2024). "This could lead to assessments of the function of BRCA1 in ovarian somatic cells across ageing and in response to genotoxic insults, such as anti-cancer agents." (PMID 39084071, 2024). "Mitotic mis-segregation of chromosomal fragments into micronuclei that accumulate and rupture in BRCA1-deficient cells can give rise to cytosolic dsDNA that stimulates cGAS-STING and inflammatory signaling, which may drive cancer initiation." (PMID 39159817, 2024). "This preliminary result could consolidate evidence of POF development in carriers and BRCA1/2 roles in cancer progression." (PMID 38792636, 2024). "On one hand, in cancer cells expressing SYCP2, loss of SYCP2 results in a significant reduction in HR activity, suggesting that SYCP2 may facilitate BRCA1/2-mediated HR." (PMID 38383600, 2024). "Our earlier research, despite not demonstrating statistically significant reductions in cancer risk associated with blood zinc levels in BRCA1 mutation carriers, indicated trends." (PMID 39061909, 2024).
cancer (continued). "Hence, for patients with endometrioid or clear cell histology or those with a significant personal or family history of LS-related cancers, like endometrial and colorectal cancer, LS and BRCA1/2 genetic testing should be considered." (PMID 38792636, 2024). "55%—72% of women who inherit BRCA1 gene will experience BC as per national cancer institute." (PMID 38539179, 2024). "Future work will be needed to address whether this hierarchy in the 53BP1 pathway will also be reflected in the clinical penetrance of mutations affecting 53BP1 and its effector genes in therapy-resistant BRCA1-mutant cancers." (PMID 39227718, 2024). "In murine models, the loss of 53BP1, in part rescues BRCA1 deficiency; however, this interaction is not commonly observed in human cancers." (PMID 39198848, 2024). "Moreover, BRCA1/2-mutant cancer cells are particularly sensitive to PARPi, creating a therapeutic window for selective cancer cell targeting." (PMID 38391958, 2024). "Nearly 25% of the patients who were germline BRCA1/2 mutation carriers in this study had no known family history of BRCA-related cancers, thus emphasizing the importance of not limiting BRCA1/2 genetic testing to those who have family history." (PMID 38817906, 2024). "Furthermore, Brca1 loss induces the expression of EMT (epithelial-to-mesenchymal transition) related genes, which are associated with the expansion of cancer stem cells and the formation of basal-like tumors in mice." (PMID 38835038, 2024). "Insufficient BRCA1 (haploinsufficiency) impairs DDR and reduces the ability to repress estrogen receptor (ER-α) signaling, thus inducing genetic mutations and leading to cancer in mammary and ovarian epithelial cells." (PMID 38543119, 2024). "In contrast to the CHEK2-deficient cancers, BRCA1/2-deficient cancers did not present with mutational signature SBS1 (0/28 cancers; 0%; P < .05), and a minority presented with mutational signature SBS5 (11/28 cancers; 39%; P < .05)." (PMID 38848470, 2024). "The type of mutation is not the only determining aspect when assessing cancer risk in offspring inheriting the BRCA-1 or BRCA-2 pathogenic variant." (PMID 39176249, 2024). "The BRCA1 and BRCA2 mutations lead to malignant tumors in the breast, ovary, and pancreas." (PMID 38730578, 2024). "PARP is an enzyme involved in DNA transcription and repair, and its inhibition is useful to treat tumors with mutations in BRCA1 (breast cancer gene 1) and BRCA2 (breast cancer gene 2) and other genes involved in the repair of homologous recombination deficits." (PMID 38965194, 2024). "Larger feasibility studies should consider anti-progestin use or Mifepristone for its potential role in BRCA1 mutation carriers, as part of individualized chemoprevention, given its beneficial experimental effects in HGSOC and cancer field defects in normal human breast tissue." (PMID 38539519, 2024). "These pathways include DNA Double-Strand Break Repair by Homologous Recombination (-log p = 4.06), Molecular Mechanisms of Cancer (-log p = 2.88), HIF1α Signaling (-log p = 2.84), Role of BRCA1 in DNA Damage Response (-log p = 2.59) and Wound Healing Signaling Pathway (-log p = 2.35)." (PMID 37694778, 2024). "Consequently, the exploration of utilizing PARP inhibitors for treating BRCA1/2 wild-type cancer patients has piqued the interest of researchers." (PMID 39156700, 2024).
cancer (continued). "BRCA1 has been implicated in promoting autophagy under cellular stress conditions, while BRCA2 deficiency has been associated with impaired autophagy flux, potentially contributing to cancer development and treatment resistance." (PMID 39199310, 2024). "From a cancer perspective, the most informative of these is a challenge provided and assessed by members of the ENIGMA consortium, using a total of 321 germline BRCA1/BRCA2 missense and in-frame indel variants." (PMID 38389099, 2024). "In summary, our preliminary study does not confirm an association between serum zinc levels and cancer risk in BRCA1 mutation carriers." (PMID 38790714, 2024). "Therefore, combined treatment with PARPi and ICIs should theoretically enhance anticancer response, particularly to cancers with high TMB and increased neoantigen expression, such as those with BRCA1/2 mutations or HRD profiles." (PMID 38542143, 2024). "Based on their findings, almost one-third of the under-examination individuals had at least one type of cancer, with prostate cancer being the most common (2 patients in the BRCA1 group and 11 patients in the BRCA2 group), followed by breast, skin and urothelial cancer." (PMID 38534919, 2024). "Some of the known variants, which have previously been associated with other cancer types, were found in the validation cohort of 121 BRCA1/2 negative familial BC patients." (PMID 39272813, 2024). "This fork recovery pathway depends on ubiquitination of PCNA at lysine 164 and is specifically activated in BRCA1- but not BRCA2-deficient cancer cells." (PMID 38943334, 2024). "Background/Objectives: BRCA1, BRCA2, ATM, and CHEK2 are known cancer predisposition genes (CPGs), but tumor risk in patients with simultaneous pathogenic variants (PVs) in CPGs remains largely unknown." (PMID 38929805, 2024). "All 352 male probands with HBOC syndrome-associated tumours, after appropriate genetic counselling, aimed at ascertaining the criteria concerning personal and family history of cancer recommended by the AIOM national guidelines, were genetically tested for germline variants in BRCA1 and BRCA2 genes." (PMID 38974244, 2024). "We also provide preliminary evidence for the potential clinical relevance of this novel fork recovery pathway in BRCA1-mutated cancers, as RAD18 is over-expressed in BRCA1-deficient cancers, and RAD18 loss compromises cell viability in BRCA1-deficient cancer cells." (PMID 38943334, 2024). "In addition, testing for high-penetrance genes beyond BRCA1 and BRCA2 should be offered to those with a family history, and, if necessary, for moderate-penetrance genes when coupled to personal and family cancer risk information." (PMID 38491334, 2024). "Thus, BRCA1 and BRCA2 are recognized as tumor suppressors, and their loss serves as an enabling hallmark of cancer by increasing genomic instability." (PMID 39198848, 2024). "BRCA1 methylation was detected in several cancer types, albeit as a rare event." (PMID 39055334, 2024). "In addition to the OC patients, the variant BRCA1 c.4358-2A > G was also identified in the daughter (B III:1) of patient B II:2, leading to an elevated risk of cancer." (PMID 38300310, 2024). "BRCA1 and BRCA2 gene mutations account for most actionable genetic BC predispositions and are increasingly used for personalized BC management and PARP inhibitors therapy of BRCA-related cancer." (PMID 38725624, 2024). "In addition to the interactions with BRCA1 and BRCA2, we also looked at the interactions between the KIF family proteins and other ACMG cancer-associated genes." (PMID 39409999, 2024). "Both the BRCA1 PV heterozygotes with full pathology had ER+HER2- cancers." (PMID 38609177, 2024).